VEGFA (vascular endothelial growth factor A)
Diseases named in the same sentence as VEGFA in open-access papers (continued):
Sharing a sentence is not in itself a finding about the gene and the disease.
tumor (continued). "In tumor tissue, expression of VEGFA was positively correlated with those ofPELP1." (PMID 35053547, 2022). "VEGFA is a major factor driving tumor vascular bed dilation." (PMID 36238299, 2022). "In benign endometrium, the increase in HIF1α protein and VEGFA protein and gene expression in post-hysterectomy samples compared to pre-hysterectomy samples indicates exposure of tissues to warm ischaemia intra-operatively, which was particularly evident in the functionalis glands and stroma." (PMID 35775066, 2022). "VEGFA provides oxygen for tumor growth by promoting tumor angiogenesis." (PMID 36046463, 2022). "Finally, to explore the involvement of MMP9 in angiogenic and invasive processes, we concomitantly analyzed the baseline plasma expression of five related factors implicated in the tumor microenvironment: MMP2, VEGFA, VEGFR2, CXCR4, and CXCL12." (PMID 34980260, 2022). "Furthermore, up-regulation of miR-128 in NSCLC cells and HUVECs not only causes down-regulation of VEGFA, VEGFR2, and VEGFR3 but also inhibits angiogenesis and lymphangiogenesis in tumor xenografts." (PMID 35918758, 2022). "Moreover, miR-150-5p in CRC can inhibit HUVEC tube-forming ability and inhibit CRC tumor progression by targeting VEGFA in CRC through VEGFA/VEGFR2/Akt/mTOR signaling pathway." (PMID 35574420, 2022). "Given the specific inhibitory effects of VEGFA on tumor-reactive, cytotoxic CD8+ T cells, a VEGFA-trap directed to activated CD8+ T cells may improve antitumor T cell activities in VEGFA-rich TME." (PMID 35577211, 2022). "A feedback mechanism in tumor cells may be activated by angiogenic inhibitors to restore VEGFA–VEGFR signaling." (PMID 35171372, 2022). "CXC chemokines and VEGFA are heavily regulated during tumor angiogenesis." (PMID 36246978, 2022). "Tumor formation creates a hypoxic microenvironment that activates hypoxia-inducible factor 1α (HIF1α) and nuclear transcription factor-κB, ultimately triggering vascular endothelial growth factor A (VEGF-A) secretion and the subsequent angiogenesis." (PMID 36092163, 2022). "It has been reported that VEGFA contributes to inhibiting apoptosis and also to stimulating the proliferation and migration of endothelial cells, followed by the collapse of blood vessels and tumor regression." (PMID 35241153, 2022). "This SIRT interacts directly with signal transducer and activator of transcription 3 (STAT3) regulating its phosphorylation and its translocation in the nucleus, thus causing an increase in vascular endothelial growth factor A (VEGFA) secretion furthering angiogenesis, tumor survival and growth." (PMID 35328633, 2022). "An increasing amount of evidence suggests that many proangiogenic factors which come from tumour cells, such as S1P, IL-6 and VEGFA, could induce the activation of STAT3 and stimulate the ECs of neighbouring blood vessels." (PMID 36068200, 2022). "Notably, VEGFA appears to be down-regulated so that vascularization of tumor tissue can be suppressed." (PMID 35456457, 2022). "VEGFA (known as VEGF) is the major angiogenic factor for tumor angiogenesis." (PMID 36428615, 2022). "With the HIF1/VEGFA signaling pathway shown to play a crucial role in tumor angiogenesis." (PMID 35292059, 2022). "As previously demonstrated, the expression of miRNAs might significantly influence tumor biology through the regulation of target genes, such as VEGFA." (PMID 35806488, 2022). "There has been increasing evidence that monocytes are essential premetastatic promoters and are rapidly recruited from the bone marrow, mainly via the CCL2/CCR2 axis, to premetastatic niches, where they promote tumor colonization by secreting angiogenic factors such as VEGFA." (PMID 36460981, 2022).
tumor (continued). "Additionally, Krüppel-like factor 8 (KLF8) cooperates with FAK to promote VEGFA expression consequent to angiogenesis and tumor growth." (PMID 35163650, 2022). "In addition, in vivo experiments have indicated that VEGFA has lower expression in MCF-7 tumor xenografts when the tumor stably expressed miR-140-5p." (PMID 35499045, 2022). "In addition to VEGFC/D in the VEGF family, VEGFA has been found to be involved in tumor lymphangiogenesis." (PMID 34552874, 2021). "VEGFA is a regulatory factor for angiogenesis and could directly promote the angiogenesis in tumour tissues and indirectly promote lymph node metastases." (PMID 34262419, 2021). "VEGFA is the only gene present in the human and mouse genomes suggesting that R-ketorolac has distinct effects on tumor (human) or mouse (tumor microenvironment) tumor components." (PMID 33413202, 2021). "FasL expression was induced by tumour-derived VEGFA, IL-10 and prostaglandin E2 (PGE2)." (PMID 34885021, 2021). "The reduction of VEGFA level is conductive to inhibit tumor cells invasion." (PMID 34289832, 2021). "VEGFA is the most potent mediator of angiogenesis and promotes unrestricted tumor growth in TNBC." (PMID 34059068, 2021). "VEGFA is a critical mediator of tumor angiogenesis and a well-characterized target of HIF-1." (PMID 34604066, 2021). "Consequently, we assessed the staining intensity of KI67, PCNA, VEGFA, and Caspase-3 in the tumor tissues using immunohistochemistry." (PMID 34544413, 2021). "VEGFA is one of the most potent mediators of angiogenesis and promotes unrestricted tumor growth." (PMID 34059068, 2021). "The SCLC tumor tissue expresses high levels of VEGFA, VEGF receptors and PD-L1." (PMID 36046087, 2021). "Overexpression miR-877-3p or inhibition of VEGFA decreased tumor volume and tumor weight." (PMID 33869051, 2021). "Interestingly, in tumor samples from the PDX models, hVEGFA was detected at high levels compared to the murine version, suggesting that a substantial part of the pro-angiogenic stimulus from VEGFA originated in the tumor cells." (PMID 34198773, 2021). "Moreover, it was described to promote pathological angiogenesis and tumor growth via p38-mediated interleukin- (IL-) 6, IL-8, and vascular endothelial growth factor-a (VEGF-A) secretion after pH decrease." (PMID 34440817, 2021). "VEGFA is secreted by tumour cells and surrounding stroma and binds to VEGFR2 (VEGF receptor-2) activating the Ras-Raf-MAPK-ERK signalling pathway stimulating the proliferation and survival of endothelial cells, leading to angiogenesis and formation of leaky and structurally abnormal blood vessels." (PMID 33917882, 2021). "Some studies have shown that VEGFA is the most major vascular growth factor in tumor angiogenesis." (PMID 34422800, 2021). "VEGFA, as a major proangiogenic factor, plays a crucial role in tumor angiogenesis." (PMID 34712608, 2021). "In CRC, HIF-1, and VEGFA are highly expressed in tumor tissue." (PMID 34680186, 2021). "For example, miRNA-199a-3p weakened tumor progression in HCC by targeting VEGFA, HGF, or MMP2." (PMID 34876904, 2021). "The major sources of VEGFA in the ocular fluids of UM patients are retina and tumor cells." (PMID 34885029, 2021). "In addition, biglycan can directly increase VEGFA expression in colon cancer cells, thereby promoting tumor angiogenesis and cancer growth." (PMID 34502094, 2021). "All these findings suggested that S1PR1 affects tumor growth by affecting P-STAT3/VEGFA signaling." (PMID 34059068, 2021). "Additionally, the data of IHC staining indicated that knockdown of MIR205HG notably inhibited the expression of VEGFA but increased the level of active caspase 3 in tumor tissues of mice." (PMID 33535182, 2021). "In fact, tumor-associated macrophages (TAMs) extracted from the tumors of mice lacking Ras–PI3K interaction had a reduced expression of VEGFA and TGF-β, two important angiogenic factors." (PMID 34356110, 2021).
tumor (continued). "The overexpression of KDM4D in gastrointestinal stromal tumor tissues activates the HIF1β gene promoter activity by decreasing the binding of H3K36me3 to the HIF1β gene promoter and induces tumor angiogenesis via the HIF1β/VEGFA signaling pathway." (PMID 34715919, 2021). "Bevacizumab, which neutralizes VEGFA secreted by tumour cells and leads to an increase in Annexin A2 with a decrease in CD44, might suggest alterations in the EVs under bevacizumab treatment." (PMID 33586248, 2021). "VEGFA showed high levels in the vitreous and anterior chamber fluid of UM patient eyes, with the latter event being positively significantly correlated with tumor diameter and tumor height." (PMID 34885029, 2021). "In addition, 5 alleviated hyperangiogenesis and hypoxia in tumor microenvironment and converted the immunosuppressive tumor microenvironment into an immunostimulatory one in VEGFA-overexpressed tumors." (PMID 34946546, 2021). "VEGFA, with the help of these pro-angiogenic molecules, induces the motility of endothelial cells and the remodelling of surrounding extracellular matrix leading to a tumour vascular network that is actively growing and infiltrative." (PMID 33544155, 2021). "Moreover, CKI also targets angiogenesis and tumour microenvironment regulating pathways through VEGFA/VEGFR2 and cytokine signalling (B cell receptor, T cell receptor and FC-epsilon signalling) respectively, which is consistent with a previous finding." (PMID 34193143, 2021). "VEGFA can induce angiogenesis by promoting the abnormal proliferation and migration of vascular endothelial cells, which is conducive to the growth, invasion, and metastasis of tumor." (PMID 33688358, 2021). "Vascular endothelial growth factor A is known to play a central role in tumor angiogenesis." (PMID 33854498, 2021). "In tumor models, CDS2 deficiency suppresses tumor growth by regulating tumor-secreted VEGFA." (PMID 34722508, 2021). "VEGFA has been shown to play an important role in tumor development." (PMID 34927541, 2021). "Moreover, research has found that activated STAT3 enhances the expression of VEGFA and then promotes the growth of the tumor vasculature." (PMID 34059068, 2021). "In the PDX models, human and murine VEGFA and PlGF were measured in tumor tissue." (PMID 34198773, 2021). "VEGFA plays a key role in tumor progression by promoting angiogenesis in the tumor tissues." (PMID 33535182, 2021). "In addition, HIF-2α was shown to regulate angiogenesis-related signaling pathways by targeting genes including vascular endothelial growth factor A (VEGFA) to promote an aggressive phenotype of tumor cells." (PMID 35096814, 2021). "In addition, research has reported that S1PR1 activity increases tumor growth by amplifying VEGFA angiogenic signaling." (PMID 34059068, 2021). "VEGFA can stimulate stromal cells to secrete hepatocyte growth factor to induce tumor progression, suggesting that VEGFA may be a promising predictor of response to sorafenib in patients with HCC." (PMID 34367979, 2021). "Cluster 0 (THBS1+MHClow TAMs) was prevalent in liver, with high expression of THBS1, MARCO and genes promoting the proliferation of EPCs and angiogenesis, such as EREG, AREG, and VEGFA, which could stimulate tumor growth and progression." (PMID 34489408, 2021). "VEGFA is a signaling protein produced by different types of cells includes macrophages, tumor cells, platelets, keratinocytes, and renal mesangial cells, which play an active role in endothelial cell functions including the formation of bones, and the angiogenesis and hematopoiesis processes." (PMID 33968364, 2021). "We also evaluated the impact of ATK1 and VEGFA activities on the tumor microenvironment." (PMID 34394377, 2021). "Activated fibroblasts (also called CAFs), which may constitute even 80% of the tumor mass, when exposed to hypoxia, also secrete elevated level of VEGFA and IL-6 compared to the cells cultured in normoxia." (PMID 33918883, 2021).
tumor (continued). "Moreover, VEGFA protein levels were significantly downregulated and cleaved caspase-3 levels were significantly increased in tumor tissues derived from MIR205HG-silenced A375 cells compared to the controls." (PMID 33535182, 2021). "Protein–protein interaction of the gene in the ceRNA networks shown that the high-scoring proteins were obtained including CD44, MYC, CCND1, ESR1, IL6, and VEGFA, which suggesting that they might jointly regulate the occurrence and development of tumor." (PMID 34655361, 2021). "In this sense, we also acknowledge that potential dysregulation of inflammation-related genes included in our proposed molecular signature (e.g., IL1A, MCM2, MMP1, MMP12, and VEGFA) might be due to the inflammation favoring tumor maintenance and progression." (PMID 34638231, 2021). "This in turn can promote tumor growth and angiogenesis, and thus VEGFA expression may become a new tumor biomarker." (PMID 34927541, 2021). "The enhanced activation of COX2 has been demonstrated in a variety of cell types in the tumor environment, and it encourages angiogenesis via increased VEGFA production, endothelial cells’ mobilization, vascular sprouting, and expanded endothelial cells’ survival." (PMID 34576107, 2021). "In addition, the authors of this study observed that miR-205-5p directly targeted the 3′ UTR of VEGFA, concluding that miR-205-5p acts as a tumor suppressor by targeting VEGFA and PI3K/Akt signaling." (PMID 33918154, 2021). "VEGFA is a crucial invasion and metastasis factor for tumor metastasis." (PMID 34289832, 2021). "Moreover, VEGFA, an important factor promoting angiogenesis, is one of the tumor markers for screening BC and predicting tumor lymphatic metastasis." (PMID 34306080, 2021). "On a molecular basis, EA or EA combined with GCB obviously reduced the intratumoral expression of Smad 2 and Smad 3, reduced angiogenesis within tumor burden and had inhibitory effects on vascular endothelial growth factor-A (VEGFA), a TGFβ signaling transactivated proangiogenic factor." (PMID 33922395, 2021). "Furthermore, our data showed that the circ_0018289/miR-183-5p/TMED5 axis contributed to an elevated expression of VEGFA and FGF2, two angiogenesis inducers, leading to induction of tumor-associated angiogenesis." (PMID 34404391, 2021). "MCM2 and VEGFA, also targets of miR-145-5p, were overexpressed in our tumor samples." (PMID 34638231, 2021). "Vascular endothelial growth factor A (VEGFA) plays an important role in tumor angiogenesis." (PMID 34217310, 2021). "Upregulation of VEGFA at 6p21.1 in C2 could increase the malignancy of tumor cells and was often accompanied by hypoxia, angiogenesis, and immunosuppressive TME, suggesting tolerance to immunotherapy." (PMID 35223867, 2021). "Angiogenesis contributes to tumor growth, and VEGFA is a potent inducer of angiogenesis in vivo." (PMID 33713575, 2021). "In order to extend the pathway regulated by circSMARCA5 to upstream signals, we investigated the expression of: (i) circSMARCA5, (ii) mRNA of its negative regulator DHX9 (see Discussion), and (iii) Iso8a and Iso8b VEGFA mRNA isoforms in a cohort of 28 GBM tumor biopsies." (PMID 33562358, 2021). "VEGFA is a primary factor driving the tumor vascular formation." (PMID 34226531, 2021). "For a long time, it has been theorized that the tumor vasculature is under constant and simultaneous control of proangiogenic and antiangiogenic factors, with vascular endothelial growth factor-A (VEGFA) representing a well-known paradigm of angiogenesis inducers." (PMID 33927723, 2021). "The results showed that VEGFA was related to the degree of tumor differentiation." (PMID 33869051, 2021). "The tumor-specific SE-associated genes were enriched in important pathways, such as chordate embryonic development (RUNX2, FOXA1), regulation of cell adhesion (RUNX1, SOX2 and VEGFA), and epithelial cell differentiation (SOX9, ELF3)." (PMID 34001209, 2021).
tumor (continued). "The key player of tumor angiogenesis is VEGFA, signaling mainly through VEGF receptor 2 (VEGFR2)." (PMID 32560565, 2020). "Endorepellin acts through the dual engagement of α2β1 and VEGFR2, causing rapid internalization and downregulation of both receptors, a mechanism referred to as dual receptor antagonism, ultimately leading to transcriptional repression of HIF-1α and VEGFA, and anti-tumor effects." (PMID 32456248, 2020). "In tumor tissue, basic fibroblast growth factor (bFGF) and vascular endothelial growth factor A (VEGFA) promote tumorigenesis by activating angiogenesis, but targeting single factor may produce drug resistance and compensatory angiogenesis." (PMID 32944017, 2020). "Furthermore, M2-like macrophages recruited to the perivascular sites within the tumor dramatically enhance angiogenesis, in part through upregulated production of VEGFa, and promote tumor cell intravasation in mammary tumors." (PMID 32708944, 2020). "In this study, we revealed that ZLM-7 could inhibit tumor growth and angiogenesis of BC, which largely depended on inhibitory of VEGFA expression via suppressing miR-212-3p/Sp1 signal axis." (PMID 33187481, 2020). "In practice, others have found that tumor hypoxia upregulates CCL28, a chemokine that recruits CD4+CD25+FOXP3+ Treg cells in an ovarian cancer mouse model, linking it to a more tolerigenic TME and increased tumor vascularization via vascular endothelial growth factor A." (PMID 35310881, 2020). "Since VEGFA has been reported functional in tumor growth and survival instead of only angiogenesis, it might be an important target of miR-106a-5p for tumor suppression." (PMID 33224312, 2020). "This multi‐epitope Peptibody with bFGF/VEGFA might develop a promising strategy for tumor therapy and the large‐scale process would support its industrial production and pre‐clinical study in the future." (PMID 32944017, 2020). "Cancer‐associated fibroblasts (CAFs) can induce the activation of neutrophils and avoid its apoptosis, while the activation of neutrophils can induce the formation of tumor blood vessels through the secretion of VEGFA, PROK2, and other vascular endothelial growth factors." (PMID 32786144, 2020). "Additionally, platelet also promote tumor metastasis and angiogenesis by releasing various growth factors such as vascular endothelial growth factor-A." (PMID 33425738, 2020). "VEGFA expression is a marker for hypoxic tumor areas in pseudopalisading necrosis in GBM." (PMID 32545380, 2020). "HIF1α stabilized by LSD1 cooperates with CBP and MTA1 to enhance VEGFA-induced tumor angiogenesis." (PMID 32070413, 2020). "As a member of the growth factor family, VEGFA has a large capacity to stimulate the angiogenic milieu, as it can increases microvascular density and vascular permeability, which promotes tumour angiogenesis and metastasis and leads to the resistance of tumours to antiangiogenic therapy." (PMID 31973726, 2020). "Importantly, expression of the invasion and angiogenesis genes, S100A10, SERPINE1, and VEGFA, increased with tumor grade, and this was also observed for HIF-1α." (PMID 32867190, 2020). "Therefore, our data reveal that miR-106a-5p has a tumor suppressor role in RCC by targeting VEGFA and provides a possible treatment target for ccRCC." (PMID 33224312, 2020). "VEGFA has been shown to have an important function in tumor growth, metastasis, and survival." (PMID 33224312, 2020). "It is also worth mentioning that most of the papillary cancer samples analyzed in the present study presented early stages according to the TNM (Classification of Malignant Tumors) classification and that the levels of VEGFA gene expression increased according to the types and stages of tumor." (PMID 32824922, 2020).